PAPOLG (poly(A) polymerase gamma)
Description:
Responsible for the post-transcriptional adenylation of the 3'-terminal of mRNA precursors and several small RNAs including signal recognition particle (SRP) RNA, nuclear 7SK RNA, U2 small nuclear RNA, and ribosomal 5S RNA.
Synonyms: FLJ12972
Tractability: Small molecule: a structure with a bound ligand is known. PROTAC: ubiquitination databases record sites on it; its protein half-life has been measured.
Gene: Protein-coding gene on chromosome 2 (60,756,232 to 60,802,086, forward strand). Ensembl gene ENSG00000115421.
Subcellular location: Nucleus
Subcellular location (Human Protein Atlas): Nucleoplasm; Cytosol; Nuclear bodies
Pathways (Reactome):
Metabolism of RNA: Nuclear RNA decay; mRNA Polyadenylation
Gene Ontology:
Molecular function: metal ion binding; poly(A) RNA polymerase activity; nucleotidyltransferase activity; RNA binding
Biological process: co-transcriptional mRNA 3'-end processing, cleavage and polyadenylation pathway; RNA 3'-end processing
Cellular component: cytosol; membrane; nuclear body; nucleoplasm; nucleus
Genetic constraint (gnomAD): Loss-of-function variants: 27 observed, 79.02 expected, observed/expected ratio (o/e) 0.34, 90% interval 0.25 to 0.47. The upper end of that interval is the gene's LOEUF score, 0.47, which puts it in group 2 of 6, group 1 being the genes least tolerant of losing a copy. Missense variants: 567 observed, 777.15 expected, observed/expected ratio (o/e) 0.73, 90% interval 0.68 to 0.78. Synonymous variants: 276 observed, 267.69 expected, observed/expected ratio (o/e) 1.03, 90% interval 0.93 to 1.14.
Homologues: Orthologues: chimpanzee PAPOLG (100% identical), rabbit PAPOLG (97% identical), guinea pig PAPOLG (96% identical), pig PAPOLG (96% identical), dog PAPOLG (95% identical), macaque PAPOLG (95% identical), mouse Papolg (94% identical), rat Papolg (94% identical), zebrafish papolg (74% identical), tropical clawed frog papolg (72% identical). Paralogues in human: PAPOLA (61% identical), PAPOLB (52% identical).
Diseases named in the same sentence as PAPOLG in open-access papers:
PAPOLG is named in the same sentence as 26 diseases in open-access papers, as found by Europe PMC text mining. Sharing a sentence is not in itself a finding about the gene and the disease. The quoted sentences say what the papers report.
hepatocellular carcinoma (4 papers, 2022 to 2024). A malignant tumor that arises from hepatocytes. "LncRNA GSEC encourages the progression of hepatocellular carcinoma by targeting the miR-101-3p/SNX16/PAPOLG axis." (PMID 37842058, 2023). "constructed a GSEC/Mir-101-3p/SNX16/PAPOLG network to predict the prognosis of hepatocellular carcinoma." (PMID 37228500, 2023). "Additionally, several research reported GSEC could promote the malignant process of triple-negative breast cancer and hepatocellular carcinoma via the GSEC/miR-202-5p/AXL axis and the GSEC/miR-101-3p/SNX16/PAPOLG axis, respectively." (PMID 38409243, 2024).
follicular lymphoma (2 papers, 2019 to 2022). Follicular lymphoma is a form of non-Hodgkin lymphoma characterized by a proliferation of B cells whose nodular structure of follicular architecture is preserved. "A recent report showed that PAPOLG cloud be overexpressed as a proto-oncogene in transformed follicular lymphoma (tFL) and follicular lymphoma (FL), and played an important role in FL to tFL transformation." (PMID 35482720, 2022).
dental caries (1 paper, 2021). The decay of a tooth, in which it becomes softened, discolored, and/or porous. "Another suggestive association signal at 2p16.1 (rs11686767, P = 3.11 × 10−8), is intronic to PAPOLG which plays a role in catalyzing template-independent extension of a DNA/RNA strand The SNP is a strong eQTL for PAPOLG, however, no known role yet of this gene in odontogenesis or dental caries." (PMID 34311721, 2021).
Hodgkinlymphoma (1 paper, 2019). "In particular, recurrent gain/amplificationof the 2p15-p16.1 locus, where REL, BCL11A, PAPOLG,PUS10, and USP34 genes reside, is a common observationin different lymphoma types including classical Hodgkinlymphoma and transformedfollicular lymphoma." (PMID 31410080, 2019).
microcephaly (1 paper, 2023). A congenital or acquired developmental disorder in which the circumference of the head is smaller than normal for the person's age and sex. "Penetrant deletions for microcephaly outlined two SROs; SRO1 (p: 0.25, 2/8) including the BCL11A (cp: 0.23) and PAPOLG (cp: 0.13) genes, and SRO2 (p: 0.55, 6/11) overlapping the USP34 (cp: 0.77) and XPO1 (cp: 0.18) genes." (PMID 36807877, 2023).
cancer (2 papers, 2019 to 2021). A tumor composed of atypical neoplastic, often pleomorphic cells that invade other tissues. "PAPOLG was reported to be overexpressed insome cancer cell types such as breast, colon, ovary, andpancreas, suggesting that it may be a proto-oncogene." (PMID 31410080, 2019).
tumor (2 papers, 2013 to 2022). "SNX16 and PAPOLG high expression groups were mainly enriched in tumor and immune-related pathways." (PMID 35482720, 2022). "Moreover, the result of gene set enrichment analysis suggested that SNX16 and PAPOLG were mainly enriched in tumor- and immune-related pathways." (PMID 35482720, 2022).
PAPOLG also shares sentences with these, for which no sentence is quoted: pyelonephritis (20 papers); cystitis (8); infection (7); urinary tract infection (4); bacteremia (3); acute cystitis (1); acute pyelonephritis (1); autoimmune (1); B-cell lymphoma (1); breast carcinoma (1); colibacillosis (1); colitis (1); COVID-19 (1); cystadenoma (1); enterocolitis (1); lymphoma (1); meningitis (1); Sepsis (1); triple-negative breast carcinoma (1).